MSLN (mesothelin)
Diseases named in the same sentence as MSLN in open-access papers (continued):
Sharing a sentence is not in itself a finding about the gene and the disease.
gastric cancer (continued). "In this study, we established MSLN-specific CAR NK-92 (MSLN-CAR NK) cells and explored their antitumor activities on gastric cancer models in vitro and in vivo." (PMID 34671203, 2021). "Taken together, these results demonstrated that the expression of sPH20-IgG2 was able to enhance the tumor infiltration of anti-MSLN CAR-T cells and potentiate their anti-tumor activity against gastric cancer in vivo." (PMID 34326835, 2021). "In 5 of the 6 investigated gastric cancer cell lines (MKN-1, MKN-7, MKN-74, NUGC-4 and TMK-1), ERC/mesothelin mRNA and C-ERC protein were detected by RT-PCR, flow cytometry and immunohistochemistry." (PMID 24146039, 2014). "Therefore, N-ERC/mesothelin is not useful as a diagnostic marker of gastric cancer." (PMID 24146039, 2014). "All of the human gastric cancer cell lines, except NUGC-3, expressed ERC/mesothelin mRNA and C-ERC/mesothelin protein." (PMID 24146039, 2014). "Other targets that entered clinical trials of gastric cancer primarily included HER2 (NCT04660929), CEA (NCT05396300), MUC1 (NCT05239143), EpCAM (NCT05028933, NCT03563326), MSLN (NCT03941626), EGFR (NCT03740256), B7H3 (NCT04864821) and NKG2DL (NCT04550663), with no conclusions reported yet." (PMID 38622705, 2024). "Moreover, the MSLN, SPP1, THBS2, SPARC, FN1, IGFBP7, VCAN were up-regulated in gastric carcinoma samples, while FGA was down-regulated." (PMID 36842141, 2023). "The ability of CAR T cells to influence gastric cancer has been extensively investigated, and includes research on epithelial growth factor receptor (EGFR), epithelial cell adhesion molecule (EpCAM), and mesothelin, and has also focused on NKG2D." (PMID 36618357, 2022). "Several antigens expressed by gastric cancer cells have been identified: human epidermal growth factor receptor 2 (HER2), mucin 1 (MUC1), carcinoembryonic antigen (CEA), claudin 18.2 (CLDN18.2), and mesothelin (MSLN)." (PMID 36291891, 2022). "It is less persuasive to use Huh-7, a hepatocellular carcinoma cell line, rather than gastric cancer cell line, as MSLN negative control." (PMID 34671203, 2021). "We also detected MSLN expression to different degrees in 9 gastric cancer tissues but not in normal gastric tissue." (PMID 31463062, 2019). "The most MSLN over-expressing tumor types were synovial sarcoma (100%) ovarian (50–88%), NSCLC, endometrioid uterine adenocarcinoma (59–64%), cervical (25%), pancreatic (86–100%), colorectal (28–50%), esophageal (25–46%) and gastric carcinoma (27–58%)." (PMID 26172299, 2015). "N-ERC/mesothelin was secreted into the supernatants of gastric cancer cell lines, but does not appear to be a useful serum marker of gastric cancer." (PMID 24146039, 2014). "The serum level of N-ERC/mesothelin is reported to increase with age, and our initial analysis without age-matching produced biased results since the gastric cancer patients tended to be older than the healthy controls." (PMID 24146039, 2014). "In gastric cancer patients, the MSLN positive group had significantly more nodal involvement and significantly deeper tumor invasion than the MSLN negative group." (PMID 22485139, 2012). "Furthermore, the expression pattern of MSLN is dynamic rather than static, demonstrating variability correlating with gastric cancer progression." (PMID 41400642, 2025). "Gastric cancer patients with high expression levels of FN1 (HR = 1.54, P < 0.05), MAC25 (HR = 1.48, P < 0.05), THBS2 (HR = 1.55, P < 0.05), VCAN (HR = 1.32, P = 0.0031), SPARC (HR = 1.42, P < 0.05), MSLN (HR = 1.28, P = 0.0066), and FGA (HR = 1.37, P < 0.05) had shorter survival time." (PMID 36842141, 2023). "ERC/mesothelin is endogenously expressed in the peritoneal mesothelium, and future studies should examine whether the serum N-ERC/mesothelin level could be used as a marker of peritoneal invasion by gastric cancer." (PMID 24146039, 2014).
gastric cancer (continued). "In addition, in our immunohistochemical analysis, MSLN was positively detected in 54.7% of 75 human primary gastric cancer samples, whereas absent in normal gastric tissue (data not shown), which indicated MSLN might be an ideal target for gastric cancer." (PMID 34671203, 2021). "Therefore, N-ERC/mesothelin does not appear to be useful as a serum marker of gastric cancer." (PMID 24146039, 2014). "Multiple studies have validated MSLN as an attractive target for CAR T or NK immunotherapy in solid tumors 14, 15; however, using CAR NK cells to target MSLN against gastric cancer has never been explored." (PMID 34671203, 2021). "Gastric cancer tissue also expresses C-ERC/mesothelin, but the significance of serum N-ERC levels for diagnosing gastric cancer has not yet been studied." (PMID 24146039, 2014). "In conclusion, N-ERC/mesothelin was secreted into the culture supernatants of gastric cancer cell lines; however, increased serum N-ERC/mesothelin concentrations were not specific to gastric cancer patients." (PMID 24146039, 2014).
malignant pleural mesothelioma (49 papers, 2013 to 2025). A malignant neoplasm that arises from mesothelial cells in the pleura and shows a diffuse growth pattern. "We showed here that MSLN expression remodeled the immune matrix of tumor microenvironment mitigating the risk of death in patients with malignant pleural mesothelioma." (PMID 37901248, 2023). "We evaluated possible diagnostic and prognostic values of serum midkine in malignant pleural mesothelioma in comparison with those of serum mesothelin, a well-established diagnostic biomarker." (PMID 28335760, 2017). "MSLN is particularly highly expressed in several types of human malignant tumors, such as ovarian serous carcinoma, pancreatic adenocarcinoma, and malignant pleural mesothelioma." (PMID 41154660, 2025). "In this context, the United States Food and Drug Administration (FDA) has validated mesothelin as a useful marker in malignant pleural mesothelioma, contributing to the assessment of response to chemotherapy and detection of recurrences." (PMID 39629295, 2024). "(2021) used Pembrolizumab as an extrinsic PD-1 blockade along with mesothelin-specific CAR-T cells in a group of 16 patients with malignant pleural mesothelioma (MPM)." (PMID 38799440, 2024). "An open-label phase I investigated the use of regionally delivered autologous mesothelin-targeted CAR-T with pembrolizumab for malignant pleural mesothelioma (MPM)." (PMID 36765623, 2023). "Accordingly, in malignant pleural mesothelioma and neuroblastoma, tumor infiltration was improved through CCR2b-expression in mesothelin- and GD2-targeting CAR-T cells, respectively." (PMID 36717905, 2023). "MSLN is related to chemotherapy resistance, and downregulation of MSLN can restore cell sensitivity to cisplatin in malignant pleural mesothelioma." (PMID 36900151, 2023). "Studies have shown that knocking down MSLN in malignant pleural mesothelioma enhances the sensitivity of tumors to cisplatin." (PMID 35692779, 2022). "Trials with anti-mesothelin CARs and anti-cMet CARs against malignant pleural mesothelioma (NCT01355965), metastatic pancreatic ductal adenocarcinoma (NCT01897415) and metastatic triple-negative breast cancer (NCT01837602) have been completed." (PMID 32899932, 2020). "In our study, a combination of MMP-7, Mesothelin and Osteopontin, showed the best significant model for distinguishing malignant pleural mesothelioma from metastatic adenocarcinoma patients." (PMID 32731396, 2020). "Phase I clinical trials have been initiated to investigate the efficacy of these IVT CAR T cells redirected for mesothelin (CARTmeso cells) in malignant pleural mesothelioma patients and other tumors that overexpress mesothelin." (PMID 32899932, 2020). "Serum mesothelin showed moderate sensitivity and high specificity to differentiate malignant pleural mesothelioma from metastatic malignancy to pleura and from benign pleural diseases." (PMID 28335760, 2017). "Soluble mesothelin is beneficial to detect the progression and the treatment response of malignant pleural mesothelioma." (PMID 28507279, 2017). "Hazard ratio with 95% CI was used to evaluate the prognostic value of soluble mesothelin and the effect of clinicopathological characteristics on the survival of malignant pleural mesothelioma." (PMID 28507279, 2017). "The results showed that soluble mesothelin level was significantly correlated with the survival of malignant pleural mesothelioma (pooled HR: 1.958, 95%CI: 1.531-2.504, p = 0.000; heterogeneity test: I2 = 1.1%, p = 0.421)." (PMID 28507279, 2017). "Soluble form of MSLN is found in the circulation in some cancer patients and monitoring the level of soluble MSLN is useful for diagnosis of malignant pleural mesothelioma." (PMID 25883990, 2015). "Serum mesothelin is currently considered the best available serum biomarker of malignant pleural mesothelioma." (PMID 23617783, 2013).
malignant pleural mesothelioma (continued). "Moreover, CAR-T cells targeting MSLN were administered to patients with pancreatic ductal adenocarcinoma, malignant pleural mesothelioma and OC who participated in a phase I clinical trial (NCT02159716)." (PMID 36717905, 2023). "Using a cut-off of 1.06 for the DNA integrity index, a cut-off of 12.91 nM for pleural fluid Mesothelin and a cut-off of 1.34 nM for serum Mesothelin, the authors obtained a specificity of 90% and a sensitivity of 75% to distinguish malignant pleural mesothelioma from benign pleural effusion." (PMID 31475103, 2019). "In some cases, mesothelin expression has been associated with increased tumor aggressiveness and poor clinical outcome, however, its impact on the clinical outcome of malignant pleural mesothelioma patients has not been extensively evaluated." (PMID 28460459, 2017). "Taken together, candidate biomarkers (Galectin-1, Mesothelin, Osteopontin, shed SDC-1, VEGF, MMP-7, HGF, TIMP-1 and NRG1-β1) identified in the current study could be diagnostic biomarkers for distinguishing malignant pleural mesothelioma and metastatic adenocarcinoma from benign patients." (PMID 32731396, 2020). "Furthermore, high soluble mesothelin level may lead to a poor prognosis for malignant pleural mesothelioma patients." (PMID 28507279, 2017). "Here, the miR-CATCH technique was applied to the mesothelin (MSLN) gene and coupled with next generation sequencing (NGS), to identify miRNAs that regulate MSLN mRNA and that may be responsible for its increased protein levels found in malignant pleural mesothelioma (MPM)." (PMID 28125734, 2017). "However, the prognostic value of soluble mesothelin in malignant pleural mesothelioma remains unclear." (PMID 28507279, 2017). "Furthermore, mesothelin immunohistochemistry could be useful for the prognostication of malignant pleural mesothelioma patients." (PMID 28460459, 2017). "(2021) conducted a phase I trial combining Pembrolizumab, an anti PD-1 agent, with regional mesothelin-targeted CAR-T cell therapy against patients with malignant pleural disease, including metastatic breast, lung, and malignant pleural mesothelioma (MPM)." (PMID 38799440, 2024). "In fact, a recently published clinical case report showed that mesothelin-directed CAR T cells were able to mediate tumor regression in two patients; the first with malignant pleural mesothelioma and the second patients with pancreatic ductal adenocarcinoma." (PMID 29113296, 2017). "However, a larger study of conventional lentivirally transduced anti-mesothelin specific CAR T-cell therapy (CD3-zeta, 4-1-BB) in serous ovarian cancer, pancreatic adenocarcinoma, and malignant pleural mesothelioma showed limited clinical activity." (PMID 37371056, 2023). "In this study, 27 patients with malignant pleural disease (either as primary or pleural metastases) received intrapleural mesothelin targeting CAR-T; 25 of these patients had a diagnosis of malignant pleural mesothelioma (MPM), and 18 of them received pembrolizumab after CAR-T cell therapy." (PMID 36765623, 2023). "However, the clinical usefulness of mesothelin immunohistochemistry, including for the prognostication of malignant pleural mesothelioma patients, has not been fully examined." (PMID 28460459, 2017).
pancreatic adenocarcinoma (41 papers, 2007 to 2025). "Strikingly similar to PSCA, high transcript levels of MSLN were associated with unfavorable survival outcomes, specifically among pancreatic adenocarcinoma patients (with a p-value of 0.002)." (PMID 37894284, 2023). "Preclinical studies in a mouse model of metastatic pancreatic adenocarcinoma demonstrated that CAR-T cells targeting MSLN can induce tumor cytotoxicity and eradicate lung metastases." (PMID 38570866, 2024). "Most research on modified CAR T-cells have investigated how they target mesothelin, a protein found in 80–85% of pancreatic adenocarcinomas." (PMID 37686543, 2023). "Mesothelin is overexpressed in many pancreatic adenocarcinoma cases and has high abundance on the tumour itself, meaning it has become a prominent target for CAR T-cell therapy." (PMID 37686543, 2023). "The highest frequencies of MSLN positivity were seen in different subtypes of ovarian (65% to 97%) and endometrium (45% to 71%) carcinomas, pancreatic adenocarcinoma (75% and 81%), malignant mesothelioma (69%), and adenocarcinoma of the lung (55%)." (PMID 33917081, 2021). "LMB-100 is currently in Phase I/II trials in patients with mesothelioma, cholangiocarcinoma and pancreatic adenocarcinoma; however, the potential of mesothelin-targeted ITX in CRC has been overlooked." (PMID 34829955, 2021). "The results indicate a specific mesothelin-driven tumor uptake of targeted 89Zr-labeled antibody which visualizes human mesothelin expressing pancreatic adenocarcinoma in real time." (PMID 26536664, 2015). "Mesothelin is overexpressed in mesothelioma, ovarian cancers, and in 70–100% of pancreatic adenocarcinomas." (PMID 26536664, 2015). "The cancer entities with highest prevalence and also highest levels of MSLN expression included all types of ovarian and endometrium carcinomas, pancreatic adenocarcinoma, malignant mesothelioma, and adenocarcinomas of the lung, stomach, esophagus, and the colorectum." (PMID 33917081, 2021). "Mesothelin could also be detected in the Panc02 murine pancreatic adenocarcinoma cell line by Western blot and flow cytometry." (PMID 29474384, 2018). "We describe here the expression of mesothelin in murine tissues and cancer cells and show that its overexpression has little effect on cell proliferation or anchorage independence, yet mesothelin overexpression impedes tumor growth in the murine pancreatic adenocarcinoma Panc02 model." (PMID 26931187, 2016). "We next investigated whether serum N-ERC/mesothelin levels were affected by treatment of pancreas adenocarcinoma with the chemotherapeutic drug gemcitabine." (PMID 25347530, 2014). "MSLN is detected in over 70% of fine needle aspirates (FNA) of pancreatic adenocarcinomas." (PMID 22485139, 2012). "One of the cell lines used as a model for studying the biology of PC is AsPC-1—human pancreatic adenocarcinoma cell line—which expresses such TAA as carcino-embryonic antigens (CEA, also referred to as CEACAM5) and mesothelin (MSLN)." (PMID 38201305, 2024). "We identified seven prognostic genes (MET, DYNLL2, CDK1, TNFSF10, PIP5K1C, MSLN, GKN1) and validated that their related proteins, such as EGFR and MMP2, have a significant impact on the prognosis of pancreatic adenocarcinoma." (PMID 37370756, 2023). "Compared with normal tissues, the expression levels of MET, DYNLL2, CDK1, TNFSF10, PIP5K1C, MSLN, and GKN1 were significantly increased in pancreatic adenocarcinoma cells (p < 0.05)." (PMID 37370756, 2023). "Pancreatic adenocarcinoma cells, CFPAC-1 and BxPC-3, and lung mesothelioma cells, MSTO-211H and NCI-H226, were positive for soluble MSLN." (PMID 25883990, 2015). "For example, in 2001, SAGE was used to first demonstrate that mesothelin and prostate stem cell antigen (PSCA) were overexpressed in pancreatic adenocarcinoma." (PMID 18954444, 2008). "At present, there is no report that MSLN and GKN1 are prognostic risk genes for pancreatic adenocarcinoma." (PMID 37370756, 2023).
pancreatic adenocarcinoma (continued). "However, in pancreatic adenocarcinoma, although MSLN is commonly expressed, it does not correlate with cancer aggressiveness, indicating that MSLN’s expression and its impact on prognosis vary by cancer type." (PMID 40227616, 2025). "Pancreatic adenocarcinoma cells, CFPAC-1 and BxPC-3, excreted soluble MSLN but epithelioid carcinoma, PANC-1, did not." (PMID 25883990, 2015).